INS (insulin)
Diseases named in the same sentence as INS in open-access papers (continued):
Sharing a sentence is not in itself a finding about the gene and the disease.
Impaired glucose tolerance (continued). "When the same plot was drawn for 2 h RBG of OGTT test and insulin levels, apart from a few children with impaired glucose tolerance (>7.8 mmol/L), the majority seemed to be well controlled." (PMID 28754153, 2017). "These mice also exhibited increased fasting blood glucose levels, impaired glucose tolerance upon glucose loading and reduced insulin sensitivity after insulin injection compared with control mice." (PMID 28266632, 2017). "The L-DKO mice had markedly elevated circulating insulin levels, impaired glucose tolerance and showed a trend toward increased rates of hepatic glucose output when given pyruvate." (PMID 29983910, 2017). "T2D is also characterized by defects in pancreatic beta cell function and insulin sensitivity, which have been demonstrated long before overt diabetes in individuals with impaired glucose tolerance." (PMID 28713332, 2017). "In light of the HOMA2-IR test results, we further our investigation to determine if P2rx7−/− mice had impaired glucose tolerance and/or were insulin resistant." (PMID 29018292, 2017). "A further aim was to evaluate any possible association between serum zinc level and beta-cell function, insulin resistance, insulin sensitivity and related impaired glucose tolerance in beta-thalassemia major patients." (PMID 29340122, 2017). "Our investigation also suggest that Gallic acid and ellagic acid rich Syzygium cumini seed powder normalized the impaired glucose tolerance and circulating insulin concentration in high fat diet induced rats." (PMID 28578702, 2017). "Some of them showed normal insulin sensitivity, others impaired glucose tolerance, and finally others were diabetic." (PMID 28809783, 2017). "The offspring from the normal zygotes injected with the total sperm RNAs or tRNAs from the male mice given a high-fat diet developed impaired glucose tolerance, showing higher blood glucose and serum insulin levels." (PMID 28978041, 2017). "The F2-HF offspring had a high birth weight and maintained a higher body mass at the age of week 3 and 12, along with an impaired glucose tolerance and lower serum insulin levels compared with the F2-SC." (PMID 29118817, 2017). "Mice fed a HFD and overexpression of let-7 had impaired glucose tolerance and IR, despite having normal insulin production and secretion levels." (PMID 28574454, 2017). "In support of a diabetogenic role for the eNAMPT-monomer, eNAMPT-Ab administration reduced blood glucose and insulin levels and corrected impaired glucose tolerance (IGT) in HFD-fed mice." (PMID 27541013, 2016). "The animals in the HFD cohorts had impaired glucose tolerance (longer time to clear a given amount of glucose), indicating deranged glucose homeostasis and reduced insulin sensitivity." (PMID 27933093, 2016). "Although the F1 offspring of mothers in the GDM group had normal blood glucose levels at birth, impaired glucose tolerance and abnormal insulin and HDL levels were displayed in adulthood." (PMID 26881249, 2016). "We show for the first time that dietary intervention improves impaired glucose tolerance, impaired hippocampal insulin signaling, and cognitive deficits; however, the reduction in the levels of the InsRs was not reversible." (PMID 27676071, 2016). "The population tested was very diverse from lean insulin sensitive to obese insulin resistant subjects, some of whom had impaired glucose tolerance, so we believe the findings apply to the whole population." (PMID 27809219, 2016). "Using specific insulin and proinsulin as the key biomarkers, the present study assessed IR and β-cell dysfunction from normal to impaired glucose tolerance offspring of Chinese T2DM patients." (PMID 27746815, 2016). "Pentobarbital induces an impaired glucose tolerance and the insulin secretion is altered with a threefold increased insulin concentration at time 20 min." (PMID 27255361, 2016).
Impaired glucose tolerance (continued). "We did not perform measurement for blood glucose and insulin level in this model, but it has already been shown in different studies that long term high fat diet feeding leads to impaired glucose tolerance and elevated blood insulin levels in C57BL/6 mice." (PMID 27893783, 2016). "Animal and in vitro studies showed that Vacor damaged pancreatic β cells, which led to impaired glucose tolerance in rats and to decreased insulin release in isolated rat pancreatic islet cells and hamster insulinoma HIT-T15 cells." (PMID 26978842, 2016). "Similar to other studies, we have shown that offspring from both HF and C dams fed on HF diet from weaning to adulthood had heavier body weight, severer impaired glucose tolerance and lower insulin sensitivity level at 32 weeks of age." (PMID 27129301, 2016). "On the other hand, BCH treatment significantly improved HF/HFr-induced impaired glucose tolerance at all-time points (0.5, 1, and 2 h) and also restored increased level of fasting plasma insulin in HF/HFr-fed mice to that in control diet." (PMID 27874078, 2016). "Impaired glucose tolerance has been shown to develop with age due to a reduction in glucose induced insulin secretion or due to uncontrolled hepatic glucose output among other factors." (PMID 27598259, 2016). "Ket/Xyl induced an impaired glucose tolerance and seems to inhibit glucose‐induced insulin secretion at time 20 min." (PMID 27255361, 2016). "For example, impaired glucose tolerance was found in adult females and their insulin response to an oral glucose preload was low if they were born to rat dams fed a low protein (8% protein w/w) diet during gestation." (PMID 26561832, 2015). "Fasting glucose and insulin were within normal limits; however, five of the 10 children demonstrated moderate–severe insulin insensitivity, and one was suggestive of impaired glucose tolerance." (PMID 26286459, 2015). "M3 receptor activity in beta cells is critical for the maintenance of blood glucose homeostasis and disruption of this pathway in transgenic mice results in reduced insulin release and impaired glucose tolerance." (PMID 26132582, 2015). "The objective of this study was to explore the relationship between zinc status, impaired glucose tolerance and insulin sensitivity in Thal patients." (PMID 26043030, 2015). "Using such an experimental paradigm of forced dyssynchrony in human volunteers resulted in elevated glucose and insulin levels along with impaired glucose tolerance and pancreatic β-cell dysfunction." (PMID 25834642, 2015). "In animal models diet supplemented with PO induces impaired glucose tolerance that can be ascribed to the reduction in insulin-sensitivity." (PMID 26393565, 2015). "These mice exhibit impaired glucose tolerance, although their insulin sensitivity is unchanged in comparison to wild-type animals." (PMID 26432886, 2015). "Liver cirrhosis causes an imbalance of whole body energy metabolism, including impaired glucose tolerance, ketoacidosis and insulin resistance." (PMID 26389019, 2015). "It has previously been shown that early-life manipulations, such as short-term insulin treatment in neonatal rats, leads to increased weight gain as well as impaired glucose tolerance and insulin responsiveness into adulthood." (PMID 26155745, 2015). "An oral glucose tolerance test revealed impaired glucose tolerance and reduced plasma insulin levels in TG mice as compared with the wild-type animals." (PMID 26091000, 2015). "These mice also exhibited impaired glucose tolerance and decreased insulin sensitivity, as compared with WT control mice." (PMID 26302066, 2015). "We assume that the accumulation of free fatty acids in the silkworm hemolymph activates JNK in the fat body cells, resulting in insulin resistance and finally in the development of impaired glucose tolerance." (PMID 26024298, 2015).
Impaired glucose tolerance (continued). "In the knock-out pregnant mice, beta cell mass was decreased and this was accompanied by increased blood glucose, decreased plasma insulin and impaired glucose tolerance, hallmarks of GDM." (PMID 27158627, 2015). "Both groups fed a long-term HFD had increased body weight, blood glucose and insulin levels, as well as impaired glucose tolerance compared to mice fed a normal diet." (PMID 26539824, 2015). "In summary, we report that loss of Afmid and a reduction in Tk expression results in defective glucose stimulated insulin secretion and impaired glucose tolerance." (PMID 26432886, 2015). "Oral glucose tolerance tests revealed moderate–severe insulin insensitivity in five of 10, and impaired glucose tolerance in one." (PMID 26286459, 2015). "In this study, we sought to explore the relationship between zinc status, impaired glucose tolerance and insulin sensitivity in a contemporary sample of patients with Thal residing in the U.S." (PMID 26043030, 2015). "A similar phenomenon has also been reported for the water extract of Pu-erh tea showing its ability to inhibit the increase in blood insulin and improve impaired glucose tolerance in db/db mice." (PMID 26504484, 2015). "The high-fructose diet induced an increase in plasma glucose and impaired glucose tolerance, but chitosan supplementation decreased plasma glucose and improved impairment of glucose tolerance and insulin tolerance." (PMID 26690452, 2015). "It is unlikely that chronic high-fat diet in fathers was able to induce impaired glucose tolerance and insulin secretion in adult female rat offspring." (PMID 25880318, 2015). "Frost and Olson demonstrated that both global and pancreas-specific overexpression of let-7 in mice resulted in impaired glucose tolerance and reduced glucose-induced pancreatic insulin secretion." (PMID 25333294, 2015). "In the current study, we have found impaired glucose tolerance and increased plasma insulin levels in mice after TAC administration." (PMID 26599323, 2015). "IRS-1 knockout females are longer lived with higher circulating insulin and impaired glucose tolerance in comparison to controls." (PMID 26061745, 2015). "Several cross-sectional studies have shown that obstructive sleep apnea impaired glucose tolerance and/or insulin sensitivity, as measured by HOMA-IR, even after adjusting for BMI." (PMID 25834642, 2015). "It results from the inability of peripheral target tissues to respond appropriately to normal concentrations of circulating insulin and provokes impaired glucose tolerance despite elevated insulin concentrations." (PMID 25180703, 2014). "In OS females, impaired glucose tolerance was observed in conjunction with lower insulin, possibly indicating impaired β-cell function." (PMID 25405530, 2014). "Adiponectin levels are low in obese patients, and patients with impaired glucose tolerance it has been reported to improve insulin sensitivity and exert antiatherogenic properties." (PMID 25333960, 2014). "Excess accumulation of AT in the visceral compartment seems to independently predict insulin sensitivity, impaired glucose tolerance, elevated blood pressure, and dyslipidemia." (PMID 25400333, 2014). "The activated PSCs have deleterious effects on β-cell survival resulting in reduced β-cell mass and on β-cell function resulting in reduced insulin secretion with consequent impaired glucose tolerance." (PMID 25097548, 2014). "AMPKα2 deletion has shown to reduce insulin sensitivity, impaired glucose tolerance along with defects in insulin secretion." (PMID 24460834, 2014). "Offspring of dams fed this diet throughout pregnancy and lactation gain excess weight, become obese, insulin resistant and develop impaired glucose tolerance in adulthood." (PMID 24749062, 2014). "The diabetic rats showed elevated fasting blood glucose and plasma insulin levels, impaired glucose tolerance and reduced insulin sensitivity in accompany with obvious lipid metabolic abnormalities." (PMID 24918756, 2014).
Impaired glucose tolerance (continued). "The potent insulin-sensitizing activities of TZDs have been effective in diminishing the progression from impaired glucose tolerance to T2DM." (PMID 24915004, 2014). "In an oGTT, both schedule-fed groups had impaired glucose tolerance with higher glucose and insulin area under the curve, similar to the response in ad libitum HF fed rats, suggesting that palatable feeding schedules represent a potential metabolic threat." (PMID 24518863, 2014). "To confirm that impaired glucose tolerance in N-STZ females is related to insulin deficiency, we measured plasma insulin levels during the OGTT." (PMID 23691181, 2013). "We also found that fasting serum insulin and impaired glucose tolerance were attenuated by 6 weeks of aerobic exercise." (PMID 23326526, 2013). "Proinsulin concentrations relative to insulin are increased in both impaired glucose tolerance (IGT) and type 2 diabetes (T2DM)." (PMID 24868254, 2013). "Most non insulin dependent diabetics and patients with impaired glucose tolerance are resistant to insulin stimulated glucose uptake." (PMID 23613929, 2013). "Exendin-4 treatment of the IUGR lamb impaired glucose tolerance in vivo, reflecting reduced insulin sensitivity, and normalised glucose-stimulated insulin secretion in vitro." (PMID 23424667, 2013). "Impaired glucose tolerance is an indicator of impaired regulation of glucose metabolism and reduced peripheral insulin sensitivity." (PMID 23658795, 2013). "More importantly, HED pigs demonstrated impaired glucose tolerance and insulin response to glucose challenge, as well as signs of reduced pancreatic beta cell function." (PMID 23991090, 2013). "Emerging evidence suggests that supplementing vitamin D in individuals with impaired glucose tolerance improves insulin sensitivity, however results from those with T2DM have been inconsistent." (PMID 23915093, 2013). "RBM4 null mice display low insulin levels, smaller pancreatic islets, and impaired glucose tolerance suggesting that RBM4 is involved in the regulation of insulin expression." (PMID 24051403, 2013). "Mice with hepatic knockout of Pik3ca showed reduced insulin sensitivity, impaired glucose tolerance, and increased gluconeogenesis." (PMID 23826284, 2013). "Surprisingly, however, this same study demonstrated a reduction in insulin secretion in Slc30a8 KO mice during an intraperitoneal glucose tolerance test (IPGTT) as well as impaired glucose tolerance." (PMID 22829903, 2012). "Previously, we have shown that growth restricted male rats develop impaired glucose tolerance, partly attributed to reduced pancreatic β-cell mass and insulin secretion and sensitivity in adulthood." (PMID 23028837, 2012). "TCN1 (Chr 1, LOD = 4.41) has shown linkage to serum insulin concentrations in impaired glucose tolerance." (PMID 22957057, 2012). "During late pregnancy however, these growth restricted females developed impaired glucose tolerance despite normal first and second phase insulin response and compensatory increases in pancreatic β-cell mass." (PMID 23028837, 2012). "Similar to previous observations, these surgeries achieved normal concentrations of fasting glycemia and fasting plasma insulin, restored insulin sensitivity, and prevented progression in impaired glucose tolerance." (PMID 22686706, 2012). "T2DM is defined by impaired glucose tolerance, chronic hyperglycemia, altered insulin secretion, and complications that come from induction of oxidative stress." (PMID 23351271, 2012). "Ogg1−/− animals also have higher plasma insulin levels and impaired glucose tolerance upon HFD feeding, relative to WT counterparts." (PMID 23284747, 2012). "The db/db mice had impaired glucose tolerance and significantly elevated blood glucose levels, indicating that these mice were in an insulin resistant state." (PMID 23247284, 2012).
Impaired glucose tolerance (continued). "We have demonstrated in rodent models that older rodents are unable to increase insulin secretion in proportion to the increased demands imposed by insulin resistance, thus contributing to impaired glucose tolerance." (PMID 22675349, 2012). "Some studies performed that in population with concomitant vitamin D deficiency and impaired glucose tolerance or T2DM, vitamin D supplement was able to correct the insulin secretion and glucose tolerance, as well as HbA1c." (PMID 23351271, 2012). "Along with the increased adiposity, the OE-NPYDBH female mice displayed impaired glucose tolerance and altered insulin sensitivity or counterregulatory effect of glucose 40 min after the ip administration of glucose." (PMID 23118773, 2012). "Islet function during prediabetes stage has been shown to be abnormal, such as the delayed “first-stage” insulin releasing after glucose load, impaired glucose tolerance, and so forth." (PMID 23197974, 2012). "Impairment of first phase insulin secretion has been recognized as an early sign of β-cell dysfunction in both T2D patients as well as in subjects with impaired glucose tolerance (IGT)." (PMID 23028596, 2012). "These loci have mostly been identified using overt measures of impaired glucose tolerance or frank diabetes; however, the impact on insulin sensitivity and beta-cell function has only been assessed using proxy measures." (PMID 22350825, 2012). "We have shown that, in critically ill children with impaired glucose tolerance, β-cells can be dysfunctional, resulting in an inadequate compensatory increase in insulin release to the decreased insulin sensitivity." (PMID 21276273, 2011). "It was recently reported that chronic high-fat diet consumption in father rats induced increased body weight, adiposity, impaired glucose tolerance, and insulin sensitivity in their offspring." (PMID 22110471, 2011). "Although proband 4 is still on treatment at the age of 3, the mother of proband 2 outgrew the HH at 11 years of age, but developed impaired glucose tolerance at 14 years of age and required insulin at 23 years of age during her third trimester of pregnancy." (PMID 20573158, 2011). "T2DM is characterized by impaired glucose tolerance, insulin resistance and insufficient insulin production by the pancreatic islet β-cells." (PMID 21966503, 2011). "Impaired glucose tolerance was observed in the offspring of mild STZ diabetic rats due to lower insulin secretion in response to glucose, while insulin resistance was reported in the offspring of the severe STZ diabetic mothers." (PMID 22110471, 2011). "To begin to elucidate the mechanisms responsible for impaired glucose tolerance in caCnRIP mice, we assessed insulin secretion in vivo and in vitro." (PMID 20689817, 2010). "Accordingly, estrogen receptor α deficient (ERKO) mice develop fatty liver, have higher fasting blood glucose, plasma insulin levels and impaired glucose tolerance." (PMID 20863371, 2010). "This has been supported by data from animal studies showing that ERKO (estrogen receptor α knockout) mice develop fatty liver, hepatic insulin resistance and impaired glucose tolerance." (PMID 20863371, 2010). "In the same study treatment with the PPARγ agonist pioglitazone increased the SCD expression and insulin sensitivity in subjects with impaired glucose tolerance." (PMID 19689798, 2009). "The results of the present study confirm that impaired autonomic activity was present also in insulin resistant patients with normal glucose metabolism and in those with impaired glucose tolerance." (PMID 16670002, 2006). "The pathophysiology of impaired glucose tolerance on the other hand has been shown to be characterized by heightened peripheral insulin resistance, normal hepatic insulin sensitivity, progressive ß-cell dysfunction, reduced secretion of the insulin-tropic hormones, and deranged glucagon secretion." (PMID 41296757, 2025).